EGFR (epidermal growth factor receptor)
Diseases named in the same sentence as EGFR in open-access papers (continued):
Sharing a sentence is not in itself a finding about the gene and the disease.
chordoma (continued). "In addition, our computational analysis also disclosed a key regulatory role for miR-574-3p/EGFR pathway in chordoma." (PMID 33194623, 2020). "Erlotinib has shown a good clinical effect EGFR-positive chordoma, and could serve as the second choice for imatinib-refractory chordoma." (PMID 30775316, 2019). "Lapatinib in EGFR-positive chordomas has been investigated in a prospective phase 2 trial." (PMID 30145982, 2018). "Our micro-array data revealed that a large number of genes were differentially expressed in chordoma tissues, including EGFR, PDGFRβ, IGF-1R and MET etc., which have been identified to the potential therapeutic targets in chordoma with both clinical and molecular evidence." (PMID 29348851, 2017). "Results from a phase II trial reported a modest antitumor activity of lapatinib administered at 1500mg continuously until progression or unacceptable toxicity in advanced EGFR-positive chordomas; the clinical benefit rate was 22,2% by RECIST for the intention-to-treat population." (PMID 28775967, 2017). "In summary, this exceptionally durable response suggests that there may be merit in evaluating combined IGF-1R/INSR and EGFR inhibition in patients with chordomas that recur following failure of local treatment." (PMID 27200287, 2016). "Our findings are consistent with the reported (p‐)EGFR expression in the majority of clinical samples, and provide evidence for exploring the efficacy of EGFR inhibitors in the treatment of patients with chordoma and studying possible resistance mechanisms to these compounds in vitro and in vivo." (PMID 27102572, 2016). "MiR-608 was reported to suppress chordoma malignancy by directly targeting EGFR and Bcl-xL, but its role in other cancers is unknown." (PMID 26646451, 2016). "The expression of p‐EGFR in chordoma may be explained on the basis that epidermal growth factor (EGF) ligands are direct targets of T17, the expression of which is considered to be critical in the growth of this tumour." (PMID 27102572, 2016). "This suggests that EGFR activation is an important driver of chordoma malignancy." (PMID 24621885, 2014). "EGFR is overexpressed in up to 100% of chordoma tumors, but is amplified in up to 40% of tumors." (PMID 24621885, 2014). "It was shown that 67–100% of chordomas overexpress EGFR and 70–100% overexpress MET." (PMID 24621885, 2014). "As EGFR polysomy and amplification have been reported in chordoma, we examined EGFR copy number." (PMID 24260133, 2013). "As EGFR mutations have been reported in exons other than 18-21 in other malignancies, we sequenced all 28 exons of EGFR in our chordoma PDX; no mutations were identified." (PMID 24260133, 2013). "EGFR polysomy has been reported in a variable number of chordoma samples (17-52%) by FISH." (PMID 24260133, 2013). "There are several previous reports evaluating EGFR expression in chordoma." (PMID 24260133, 2013). "The rationale for treating chordoma with EGFR inhibitors is inspired by recent reports." (PMID 21970335, 2011). "In the light of these findings, chordoma patients may benefit from treatment with multi-kinase inhibitors targeting both EGFR and PDGFR." (PMID 22613809, 2011). "We also review the literature concerning the rationale and potential of EGFR targeting in chordoma." (PMID 21970335, 2011). "Altogether, these data clearly implicate aberrant EGFR signaling in the pathogenesis of chordoma." (PMID 21970335, 2011). "We report the fourth case of advanced chordoma treated with an EGFR inhibitor." (PMID 21970335, 2011). "Notably, it was recently shown that AKT activation persists in the UCH-1 chordoma cell line following treatment with the EGFR inhibitor tyrphostin." (PMID 22613809, 2011). "Partial response of metastatic chordoma to combined cetuximab/gefitinib treatment suggests that EGFR targeted treatment may benefit chordoma patients." (PMID 22613809, 2011).
chordoma (continued). "Furthermore, statistical analysis showed that EGFR activation was significant for chordomas, based on the analysis of our cohort." (PMID 22613809, 2011). "As for other solid tumours, most chordomas strongly express epidermal growth factor receptor (EGFR) and the hepatocyte growth factor/scatter factor receptor c-Met and some promising responses to molecularly target agents such as cetuximab and gefitinib were described." (PMID 20109225, 2010). "Specific to the CF466 sacral chordoma model, TGFA was among the most significantly reduced genes, which is notable because it encodes an EGFR ligand, and SINE compounds are effective against cancer cells with engineered resistance to EGFR-tyrosine kinase inhibitors." (PMID 36059685, 2022). "Consequently, in a bench-to-bedside approach, the current translational study aims to identify targets that synergise with EGFR/ErbB inhibitors to overcome resistance issues and, thereby, increase and prolong treatment effects for patients with advanced chordoma." (PMID 34550531, 2021). "Inhibitors or antibodies against EGFR may act as potential treatments for chordomas." (PMID 34560882, 2021). "In conclusion, the consistent activation of AKT, the recurrent activation of upstream EGFR and of downstream effectors like p70S6K and mTOR, together with frequent loss of TSC1 and PTEN gene loci, all indicate that the PI3K/AKT pathway is an important mediator of transformation in chordoma." (PMID 22613809, 2011). "Comparable results were reported also for lapatinib, a dual EGFR and human epidermal growth factor 2 (HER2) inhibitor, investigated in a phase II trial in patients with EGFR-expressing chordoma." (PMID 40627883, 2025). "Preclinical studies have identified several potential targets for chordoma drug treatment, e.g., mTOR, PI3K, PDGFR, VEGFR, and EGFR, some of which have been evaluated in single-agent clinical trials." (PMID 40901948, 2025). "A comprehensive genomic and transcriptomic analyses identified the IGF1R/FGFR/EGFR and CDK4/6 pathways as treatment strategies for chordoma patients." (PMID 41442054, 2025). "The heatmap revealed that MIR5690, SNORD15B, RAB3B were highly expressed in chordoma, along with the generally reported chordoma regulators, such as KRT19, LYST, and EGFR." (PMID 40135815, 2025). "Molecular therapy targets being investigated include several receptor tyrosine kinases (e.g., PDGFR, EGFR), downstream cascades (e.g., PI3K/Akt/mTOR), brachyury (a transcription factor unique to chordoma), and the FGF/MEK/ERK pathway." (PMID 39193055, 2024). "In 2021, a review article described 14 globally approved EGFR reversible and irreversible inhibitors for anticancer treatment, including gefitinib and erlotinib, some of which may be considered in future studies of combinatorial immunotherapy against chordoma with a special focus on CSCs." (PMID 38741774, 2024). "Similar to other carcinomas, the activity of various kinases is increased in chordoma, including vascular endothelial growth factor receptor (VEGFR), EGFR, and PDGFR." (PMID 37111759, 2023). "Our screens in chordoma similarly demonstrate dependency on both genes, but we noted that PTPN11 dependency scores are of a greater magnitude than those of EGFR." (PMID 37024492, 2023). "Activation of the PI3K/AKT/TSC1/TSC2/mTOR signaling pathway, overexpression of receptor tyrosine kinases (such as EGFR), as well as activation of IGF1R were described in chordoma and were considered as targets for tailored therapy." (PMID 36033338, 2022). "Several recent studies (including our own) have revealed that EGFR-signaling dysbiosis modulated by CMTM3 and cMET exacerbated the chordoma process, and that DEPDC1B regulated ubiquitination of BIRC5 also promoted chordoma progression." (PMID 36248973, 2022). "These de-risked leads present a potential new therapeutic avenue for treatment of chordomas and new chemical tools and probe compound 45 (UNC-CA359) to interrogate EGFR mediated disease phenotypes." (PMID 35896603, 2022).
chordoma (continued). "The first pre- and clinical results of some FDA-approved drugs targeting EGFR, PDGFR-α, PDGFR-β, and c-Kit, have shown partial objective response and clinical benefit in chordomas." (PMID 36505864, 2022). "Chordoma tumors are known to overexpress multiple kinases (included PDGFR-α, PDGFR-β, c-Kit, c-Met, pAKT, mTOR, HER2, VEGFR, and EGFR) which are involved in a multitude of cellular functions relevant to cancer pathogenesis." (PMID 36505864, 2022). "The 6-iodo 9 was more potent against EGFR (IC50 = 0.83 μM), but was still weak in the four additional chordoma cell lines (IC50 = > 100 μM) and WS1 (IC50 = 98 μM)." (PMID 35896603, 2022). "Epidermal growth factor receptor (EGFR), a member of tyrosine kinase receptors, is generally overexpressed in chordomas." (PMID 34560882, 2021). "In addition, we detected EGFR expression in CMTM3 overexpressed JHC7 and U-CH1 cells and CMTM3 silenced MUG-Chor1 cells by Real-time PCR and found that CMTM3 did not alter EGFR expression at the mRNA level, indicating CMTM3 might facilitate EGFR degradation in chordoma cells." (PMID 34560882, 2021). "All six chordoma cell lines examined expressed HLA-A, B, C/MHC-1, PD-L1, and EGFR as assessed by percent positive cells and MFI." (PMID 35765577, 2021). "We undertook a combination screen in the UM-Chor1 clival chordoma cell line and tested a panel of 133 US Food and Drug Administration (FDA)-approved anticancer drugs in combination with two EGFR/ErbB inhibitors (afatinib and erlotinib)." (PMID 34550531, 2021). "It was reported that the expression of PDGFR-α, EGFR and c-MET were increased in spinal chordoma, and tyrosine kinase inhibitor exhibited suppression effects on chordoma cells." (PMID 34868903, 2021). "As the majority of chordomas express cMET and its ligand, HGF, and crosstalks between EGFR and MET-signaling exist, we aimed to explore cMET activity in chordoma cell lines and clinical samples." (PMID 34127734, 2021). "Afatinib, another FDA-approved EGFR inhibitor used against NSCLC, had anti-proliferative activity against all chordoma cell lines tested (IC50 < 0.7 μM) except for JHC720." (PMID 32737414, 2020). "Immunohistochemical (IHC) studies have shown that RTKs, such as platelet-derived growth factor receptor (PDGFR), epidermal growth factor receptor (EGFR), MET and HER2, are expressed in chordoma." (PMID 32533822, 2020). "Afatinib, another bi-specific inhibitor of EGFR and HER2/neu, was the only agent which showed cytotoxic effects across multiple chordoma cell lines in a drug sensitivity assessment." (PMID 30775316, 2019). "Lapatinib, a bi-specific inhibitor blocking both EGFR and HER2/neu, achieved 33.3% PR and 38.9% SD as per Choi criteria and 100% SD according to RECIST in EGFR-positive chordoma." (PMID 30775316, 2019). "Further studies have reported that miR-34a and miR-608 modulate chordoma malignancy, a rare malignant tumor originating from notochord, by directly targeting BCLxL, EGFR (epidermal growth factor receptor), and MET." (PMID 29361709, 2018). "A recent study reported that most chordomas express multiple RTKs, including PDGFR isoforms, EGFR, HER2, c-MET, and KIT." (PMID 27200287, 2016).
chordoma (continued). "Four of the chordoma cell lines, U‐CH1, U‐CH7, UM‐Chor1 and MUG‐Chor1, responded to EGFR inhibition with EC50 concentrations < 1 μm, whereas U‐CH2, U‐CH10 and JHC7 were largely resistant." (PMID 27102572, 2016). "In summary, our study shows for the first time that miR-608 and miR-34a are deregulated tumor suppressive miRNAs that act via regulation of EGFR, MET and apoptosis in chordoma." (PMID 24621885, 2014). "These were miR-608, which has potential binding sites in the 3′UTR of EGFR and Bcl-xL mRNAs (which are overexpressed in almost all chordoma tumors) and miR-34a which is predicted to target MET (expressed in up to 100% of chordomas)." (PMID 24621885, 2014). "We show that EGFR and MET activations promote chordoma cell proliferation and invasion and that pharmacological inhibition of EGFR and MET inhibits chordoma cell proliferation and survival." (PMID 24621885, 2014). "To confirm the expression of EGFR and MET in chordoma specimens, we performed immunohistochemistry on chordoma tumor sections." (PMID 24621885, 2014). "We chose miR-608 and miR-34a for further study because their chromosomal loci are frequently deleted in chordoma and because they are predicted to target EGFR and MET, which are the most commonly deregulated RTKs in chordoma." (PMID 24621885, 2014). "We activated EGFR with EGF (20 ng/ml) or MET with HGF (20 ng/ml) treatment in UCH1 and C24 chordoma cells." (PMID 24621885, 2014). "EGFR and MET expression and gene amplification in chordoma in published immunohistochemical studies." (PMID 24621885, 2014). "Polysomy of the EGFR/ERBB1 gene was previously reported in a subset of chordomas, and the EGFR is an interesting target for therapy in chordoma based on the availability of targeted molecular inhibitors." (PMID 22613809, 2011). "In the literature, several RTK, specifically PDGFRA, PDGFRB, KIT, EGFR, MET and HER2, were reported to be expressed in chordoma by immunohistochemistry." (PMID 22613809, 2011). "Histopathological features of 42 chordoma specimens, 21 primary and 21 advanced, were assessed by immunohistochemistry and fluorescent in situ hybridization (FISH) using PDGFRB, CSF1R, and EGFR probes." (PMID 22613809, 2011). "Phospho-receptor tyrosine kinase analysis showed EGFR activation in the U-CH1 chordoma cell line and all of the three chordomas analyzed." (PMID 21970335, 2011). "By conventional immunostaining, we have also found that EGFR and HER2 are expressed in chordomas, albeit in a lower fraction of cases 26/39 (67%) and 5/16 (31%), respectively." (PMID 22613809, 2011). "In summary, we found that EGFR is the strongest and most frequently activated RTK in chordomas, and therefore becomes a possible target for therapy." (PMID 22613809, 2011). "Commonly reported molecular targets in chordoma include platelet derived growth factor (PDGFR), vascular endothelial growth factor receptor (VEGFR), and epidermal growth factor receptor (EGFR), insulin-like growth factors (IGF), and mammalian target of rapamycin (mTOR)." (PMID 38881706, 2024). "Other potential target classes for the combination with CDK inhibitors could be EGFR/ERBB2 inhibitors or p300 inhibitors, which have previously been reported as having antiproliferative effects on chordomas." (PMID 38786326, 2024). "Bibliometric analysis showed that chemotherapy, PTEN, EGFR, and TBXT were related to chordoma." (PMID 36520826, 2022). "RTKs, such as platelet-derived growth factor receptor (PDGFR), epidermal growth factor receptor (EGFR), fibroblast growth factor receptor (FGFR), and vascular endothelial growth factor receptor (VEGFR), are also important oncogenic regulators of chordoma." (PMID 36185236, 2022).
chordoma (continued). "Therefore, we tested the levels of total and phosphorylated p-EGFR (Tyr1068), p-STAT3 (Tyr705), p-AKT (Ser473) and p-ERK1/2 (Thr202/Tyr204) in chordoma cells by western blot." (PMID 34560882, 2021). "Drug screening programmes have revealed epidermal growth factor receptor inhibitors (EGFRis) as promising therapeutics for chordoma, an orphan malignant bone tumour, in the absence of a known genetic driver." (PMID 34550531, 2021). "p-EGFR, p-STAT3, p-AKT and p-ERK1/2 in tumor samples from the chordoma mice model." (PMID 34560882, 2021). "Six chordoma cell lines; established from 3 from clival tumor patients (UM-Chor1, MUG-CC1, UM-Chor5), and 3 sacral tumor patients (JHC7, U-CH1, U-CH2) were analyzed by flow cytometry to quantify expression surface markers MHC-I/HLA-A,B,C, PD-L1, and EGFR." (PMID 35765577, 2021). "Moreover, a variety of potential molecular targets for chordoma were identified, such as platelet-derived growth factor receptor β, PI3K/mTOR, epidermal growth factor receptor (EGFR), vascular endothelial growth factor (VEGF), and tyrosine kinase." (PMID 34330893, 2021). "For example, high levels of EGFR in the chordoma cell line JHC7 was not accompanied by activated EGFR signaling." (PMID 30775316, 2019). "Furthermore, promising advances in experimental chordoma treatment have employed RTK inhibitors, specifically compounds targeting EGFR." (PMID 31221659, 2019). "Around 40% of chordoma patients show CNG of the chromosome band 7p12, where EGFR is located." (PMID 30775316, 2019). "Of the seven chordoma cell lines tested, we demonstrated that four (U‐CH1, U‐CH7, MUG‐Chor1 and UM‐Chor1) were sensitive and three (U‐CH2, U‐CH10 and JHC7) were resistant to EGFR inhibition." (PMID 27102572, 2016). "Loss of heterozygosity for PTEN has been reported frequently in chordoma 19, 23, 24, 52, 53, 82, 83, 84; however, based on our in vitro results, it was not possible to predict response to EGFR inhibition based on PTEN expression." (PMID 27102572, 2016). "Chordomas express stem cell factor receptor (c-KIT), platelet-derived growth factor receptors (PDGFR-α and PDGFR-β), receptor tyrosine-protein kinase erbB-2 (HER2/neu), and epidermal growth factor receptor (EGFR)." (PMID 27659533, 2016). "We found high expressions of EGFR and MET in chordoma specimens." (PMID 24621885, 2014). "EGFR and MET are among very few molecules that have been shown to be deregulated in human chordoma." (PMID 24621885, 2014). "We then determined the effects of EGFR and MET activations on chordoma malignancy endpoints." (PMID 24621885, 2014). "No animal model and only few chordoma cell lines are available for preclinical drug testing, and, although no druggable genetic drivers have been identified, activation of EGFR and downstream AKT-PI3K pathways have been described." (PMID 24311731, 2014). "Therefore, copy number alterations of miR-34a and miR-608 are likely partly responsible for EGFR, MET and Bcl-xL overexpressions in chordoma as demonstrated by our study." (PMID 24621885, 2014). "In this paper, we demonstrate EGFR is a highly activated kinase in a patient-derived chordoma xenograft, erlotinib and gefitinib inhibit U-CH1 proliferation in vitro, and erlotinib inhibits growth of chordoma in vivo." (PMID 24260133, 2013). "We demonstrated that EGFR is frequently and the most significantly activated RTK in chordomas." (PMID 22613809, 2011). "Thus, the EPHB2, EGFR and macrophage-stimulating protein receptor (MSPR) were found to be significantly activated in chordoma." (PMID 22613809, 2011). "The observed potency could be related to a target other than EGFR, as the corresponding 7-iodo 32 has similar EGFR activity to 28, but was not potent in the patient-derived chordoma lines or the WS1 control (IC50 = > 100 μM)." (PMID 35896603, 2022). "However, clinical trials with EGFR inhibitors and antibodies have not established a clear therapeutic benefit in all chordoma patients." (PMID 34560882, 2021).